HAS2 (hyaluronan synthase 2)
Diseases named in the same sentence as HAS2 in open-access papers (continued):
Sharing a sentence is not in itself a finding about the gene and the disease.
astrocytoma (3 papers, 2014 to 2022). "Survival analyses indicated that elevated HAS2 staining intensity is associated with decreased overall survival of the patients and is an independent prognostic factor in infiltrating astrocytoma." (PMID 29914429, 2018). "Low HAS2 immunostaining was associated with IDH1 mutation, a known positive prognostic factor in diffusely infiltrating astrocytomas." (PMID 29914429, 2018). "In B (grade IV gliosarcoma) and D (the grade III astrocytoma) HAS2 antibody was pretreated with peptide." (PMID 29914429, 2018). "Our present data shows that increased HAS2 immunostaining intensity is a negative prognostic factor in astrocytomas associating significantly with decreased survival of patients both in univariate and multivariate tests." (PMID 29914429, 2018). "Moreover, our results show that there is an association between low HAS2 immunostaining intensity and IDH1 –mutation, which is a known positive prognostic factor in diffusely infiltrating astrocytomas." (PMID 29914429, 2018). "Our results indicate that especially HAS2 and to a lesser extent HYAL2 and HAS1 are involved in the progression of diffusely infiltrating astrocytomas." (PMID 29914429, 2018). "In A (grade I subependymal giant cell astrocytoma) and C (grade III astrocytoma) HAS2 immunostaining; brown color represents HAS2 and blue indicates nuclei." (PMID 29914429, 2018). "Since HAS2, CD44, and VEGF endogenous mRNA expression levels were very low in HRA cells although their expression levels were high in U373MG human astrocytoma cells and SH-SY5Y human neuroblastoma cells, it was impossible to evaluate the effect of 4-MU treatment (data not shown)." (PMID 25304388, 2014).
cholangiocarcinoma (3 papers, 2021 to 2025). A carcinoma that arises from the intrahepatic biliary tree (intrahepatic cholangiocarcinoma) or from the junction, or adjacent to the junction, of the right and left hepatic ducts (hilar cholangiocarcinoma). "The hyaluronan synthase 2 (HAS2) is strikingly upregulated in myCAFs and has been demonstrated to promote cholangiocarcinoma (ICC) progression." (PMID 40248695, 2025).
colitis (3 papers, 2015 to 2025). Inflammation of the colon. "Alteration of HA distribution after experimentally-induced colitis was associated with up-regulation of HAS2 expression in myenteric neurons." (PMID 29247178, 2017). "In murine colitis models, inhibition of HA synthase 2–mediated (HAS2-mediated) HA synthesis sensitized the therapeutic response to infliximab." (PMID 39782690, 2025). "We cannot exclude that HAS2 increased expression in myenteric neurons during experimentally-induced colitis is finalized to retain inflammatory cells in the proximity of myenteric ganglia, since we observed prominent leukocyte infiltration." (PMID 29247178, 2017). "After DNBS-induced colitis, the levels of HAS2 transcript and protein were significantly higher (p < 0.001) compared to control animals." (PMID 29247178, 2017). "Therefore, interfering with HAS2-mediated HA synthesis in fibroblasts sensitizes IFX therapy in colitis." (PMID 39782690, 2025). "For this purpose, we adopted a murine DSS-induced colitis model and treated mice with IFX or 4MU (a HAS2 inhibitor) alone or in combination." (PMID 39782690, 2025). "Our data suggests that HAS1 may act as a negative regulator of HA synthesis by HAS2 since both HAS1 null and HAS1/3 double null mutants displayed higher levels of HA deposition during colitis." (PMID 26448758, 2015).
diabetic nephropathy (3 papers, 2021 to 2024). "Endothelial deletion of hyaluronan synthase 2 (Has2) in mice is associated with mesangiolysis, glomerular capillary rarefaction, glomerulosclerosis and albuminuria, findings with direct implications in several disease models, including diabetic nephropathy." (PMID 33671524, 2021). "IGF-1R may also contribute to the pathogenesis of diabetic kidney disease through the induction of fibrotic genes and hyaluronan synthase 2, a key enzyme involved in the synthesis of hyaluronan, a component of the extracellular matrix." (PMID 39638246, 2024). "IGF-1 signaling via IGF-1R on MCs may contribute to the pathogenesis of diabetic kidney disease through the induction of Has2 and fibrotic genes." (PMID 39638246, 2024). "Interestingly, the only two shared InDels in patients with diabetic nephropathy were noted upstream of the neighboring gene HAS2, and this could have a potential role in the progression of tubulointerstitial fibrosis in diabetic nephropathy." (PMID 37795536, 2023).
esophageal cancer (3 papers, 2023 to 2025). A primary or metastatic malignant neoplasm involving the esophagus. "In this study, mouse dermal fibroblasts cocultured with human esophageal cancer cells exhibited upregulated mRNA expression of hyaluronan synthase 2 (Has2) and increased secretion of hyaluronan which is a component of the extracellular matrix and contributes to cancer malignancy." (PMID 39887653, 2025).
fibrosis (3 papers, 2019 to 2021). the formation of excess fibrous connective tissue in an organ or tissue in a reparative or reactive process. "Thus, in fibrosis settings, 4MU treatment (CCl4/4MU group) causes a dramatic reduction of HAS2 expression on macrophages." (PMID 31847129, 2019). "Our data is consistent with reports that 1,25D and other endogenous vitamin D steroids inhibited TGF-β1-induced HAS2 expression and HA synthesis in association with anti-fibrotic actions, reduced HA accumulation in UV-treated mouse skin and decreased serum HA in a rat fibrosis model." (PMID 32774770, 2020).
glioblastoma (3 papers, 2015 to 2023). The most malignant astrocytic tumor (WHO grade IV). "In the lung adenocarcinoma cell line A549, HAS2 was expressed at high level, but HAS3 was also expressed to a significant degree, while the glioblastoma cell line U-251MG expressed HAS2, and even higher level of HAS3." (PMID 36497283, 2022). "In addition, we performed knockout (KO) and overexpression (OE) of HAS2 in glioblastoma multiforme (GBM) cells, and observed the effects of these alterations on the behavior of cancer cells." (PMID 37636435, 2023).
influenza infection (3 papers, 2019 to 2024). "Expression of has1 peaked early during influenza infection at day 4 whereas has2 expression peaked later and was maintained above naïve mice for at least 3 weeks." (PMID 29933044, 2019). "Differential regulation of Has isoforms has been described in other lung challenge models, such as influenza, where Has1 is induced at d3 p.i. coinciding with the innate response to infection, while Has2 is increased at d6 p.i. once an adaptive response has begun." (PMID 39606183, 2024).
keloid (3 papers, 2016 to 2026). An irregularly shaped, elevated mark on the skin caused by deposits of excessive amounts of collagen during wound healing. "AMPH and TNFRSF9 are promising diagnostic biomarkers for keloid, while quercetin from Aloe vera targets HAS2 and IL6, offering therapeutic potential." (PMID 41544047, 2026). "In our investigation, IL6 and HAS2 were identified as quercetin’s anti-keloid targets through network pharmacology." (PMID 41544047, 2026). "We previously reported that HAS2 is significantly upregulated in keloid keratinocytes and contributes to their enhanced motility in vitro." (PMID 27574697, 2016). "HAS2, among the most highly upregulated genes in keloid vs. normal keratinocytes, is one of three HAS genes involved in synthesis of hyaluronic acid." (PMID 27574697, 2016). "However, the specific mechanisms of the targeted effects of quercetin and IL6/HAS2 in the treatment of keloids still need to be further explored." (PMID 41544047, 2026). "Future studies should prioritize experimental validation of AMPH/TNFRSF9 in larger cohorts, functional characterization of IL6/HAS2 in keloid models and development of quercetin topical formulations to address the clinical need for safe and effective anti-keloid treatment." (PMID 41544047, 2026). "The hyaluronan synthase 2 (HAS2) gene, encoding one of three HAS enzymes involved in biosynthesis of hyaluronan, an important part of the epidermal ECM was 4.38‐fold increased in keratinocytes from keloid." (PMID 36483731, 2022).
lipoblastoma (3 papers, 2020 to 2023). A lipoma usually occurring in the extremities of young children (usually boys). "Molecular genetic examinations of lipoblastomas revealed rearrangements of 8q11∼q13, hyaluronic acid synthase 2 (HAS2) and collagen 1 alpha 2 (COL1A2) as well as pleomorphic adenoma gene 1 (PLAG1) amplification." (PMID 31282548, 2020). "On the molecular level, lipoblastomas typically show a rearrangement of the chromosomal region 8q11–13, which results most commonly in a fusion of the pleomorphic adenoma gene 1 (PLAG1) with diverse partners, most commonly HAS2 (8q24.1) and COL1A2 (7q22)." (PMID 33814013, 2021).
oral cancer (3 papers, 2016 to 2018). "The oncogenic HA-CD44 signal is also involved in chemoresistance, and hyaluronan synthase 2 (HAS2) reportedly induces CD44-dependent CDDP resistance in oral cancer." (PMID 29849953, 2018). "We also revealed that HAS2, which is expressed by CAFs, plays a potential role in promoting the invasion of oral cancer cells." (PMID 27884164, 2016). "Our findings confirm that the HAS2-mediated MMP1 and TIMP1 changes are most likely responsible for the mechanisms underlying CAF-mediated promotion of the migration, invasion and EMT of oral cancer cells." (PMID 27884164, 2016). "Thus, CAF-derived HAS2 may be a new therapeutic target against oral cancer." (PMID 27884164, 2016). "Although HAS3 appears to play a dominant role in oral cancer, we still can not rule out the involvement of HAS1 or HAS2 in HA synthesis nor explain why reduced HA staining was a poor prognositic maker in other oral cancer cohort." (PMID 28107185, 2017). "In summary, the data presented here demonstrate that HAS2, which is expressed by CAFs, may facilitate the migration, invasion and EMT of oral cancer cells by disturbing the balance between MMP1 and TIMP1." (PMID 27884164, 2016). "Furthermore, we used a conditioned culture medium model to evaluate the effects of HAS2 from CAFs on the invasion and epithelial-mesenchymal transition (EMT) of the oral cancer cells Cal27." (PMID 27884164, 2016). "Despite the detection of both HAS1 and HAS2 in oral cancer cells, their expression levels were lower than that of HAS3 in most oral cancer cell lines not to mention that HAS1 and HAS2 are catalytically less active than HAS3 in HA synthesis." (PMID 28107185, 2017).
oral squamous cell carcinoma (3 papers, 2016 to 2023). "Several studies have shown that the inhibition of HAS2 reduced the invasion of oral squamous cell carcinoma." (PMID 30540749, 2018). "This study aimed to determine the role of hyaluronan synthase 2 (HAS2) from CAFs in the progression of oral squamous cell carcinoma (OSCC) invasion." (PMID 27884164, 2016).
pancreatic ductal adenocarcinoma (3 papers, 2016 to 2025). An infiltrating adenocarcinoma that arises from the epithelial cells of the pancreas. "It was recently shown that treating pancreatic ductal carcinoma cells with 5-aza-dC leads to increased expression of HAS2, suggesting an epigenetic mechanism is involved in regulating HAS2 in cancer cells." (PMID 27977763, 2016). "Indeed, inhibition of HAS2 upon treatment with its specific inhibitor 4-methylumbelliferone (4-MU, also known as hymecromone), has proven successful in reducing tumour stroma in pancreatic ductal adenocarcinoma (PDAC), which also shows high expression of NRG1." (PMID 33692466, 2021).
pulmonary hypertension (3 papers, 2019 to 2022). Increased pressure within the pulmonary circulation due to lung or heart disorder. "HAS2 expression is increased in an animal model of pulmonary hypertension, but decreased in pulmonary arterial smooth muscle cells in idiopathic pulmonary arterial hypertension where HAS1 is responsible for enhanced hyaluronan." (PMID 29933044, 2019).
serous ovarian cancer (3 papers, 2009 to 2019). "We examined expression of HA synthases (HAS1, HAS2, and HAS3) and hyaluronidases (HYAL1, HYAL2) in primary serous ovarian cancer cells isolated from patient ascites and CBP-resistant OV-90 cells." (PMID 31443261, 2019). "Furthermore, we showed that 4-MU inhibited expression of HAS2, HAS3 and CSC markers (ALDHA1 and ABCG2) in a 3D-spheroid culture of chemoresistant primary serous ovarian cancer cells." (PMID 31443261, 2019). "We found that HAS2 and HAS3 but not HAS1 expression is significantly increased in primary serous ovarian cancer cells isolated from the ascites of patients with chemoresistant disease compared to patients with chemosensitive disease." (PMID 31443261, 2019). "We additionally showed that expression of HAS2 and HAS3 but not HAS1 or hyaluronidases HYAL1 and HYAL2 were significantly increased in chemoresistant compared to chemosensitive primary serous ovarian cancer cells." (PMID 31443261, 2019). "Since HAS2 and HAS3 genes showed no consistent increase in their expression in the serous ovarian cancers, and HAS1 mRNA was virtually absent, changes in the transcriptional activity of the HAS genes seem not to be the main factor in the increased hyaluronan content of these tumors." (PMID 19435493, 2009).
airway hyperresponsiveness (2 papers, 2021 to 2025). "Using HAS2 gene (Has2) heterozygous-deficient (Has2+/−) mice, we also found that the attenuation of Has2 exacerbates eosinophilic airway inflammation, increases airway hyperresponsiveness, and promotes airway remodeling." (PMID 41181120, 2025). "Based on these backgrounds, mouse HAS2 gene (Has2) attenuation was recently reported to worsen acute eosinophilic airway inflammation and increase airway hyperresponsiveness (AHR) using Has2 heterozygous-deficient (Has2+/−) mice." (PMID 35069543, 2021).
bladder tumor (2 papers, 2018 to 2021). "We have earlier shown that loss of AGL results in increased HAS2 expression and HA synthesis in bladder tumors." (PMID 29682180, 2018).
Breast Invasive Carcinoma (2 papers, 2020 to 2025). "We found the overall frequency of genomic alterations in HAS2 was 27% in 1904 cases of Breast Invasive Carcinoma with complete data." (PMID 32774770, 2020). "However, among 1904 cases of breast invasive carcinoma, only 27% of the cases were found to have alterations in HAS2." (PMID 40443562, 2025).
cutaneous melanoma (2 papers, 2016 to 2018). A primary melanoma arising from atypical melanocytes in the skin. "The present work demonstrates that reduced expression of HAS1 and HAS2 is associated with an unfavorable prognosis in cutaneous melanoma." (PMID 27184066, 2016). "However, whether decreased expression of HAS1 and HAS2 is the cause or a secondary consequence of cutaneous melanoma is a question that awaits further investigation." (PMID 27184066, 2016). "Importantly, we found that coordinate expression of Id1 or Id3 with HA synthases HAS2, HAS3, and CD44 is associated with reduced overall survival of cutaneous melanoma patients." (PMID 30297743, 2018). "In the present study, we compared immunohistological staining results of HAS1 and HAS2 with clinical and histopathological parameters to investigate whether HAS1 or HAS2 has prognostic value in cutaneous melanoma." (PMID 27184066, 2016). "Consistently, coordinate expression of Id1 or Id3 with HAS2, HAS3 or CD44 significantly correlated with reduced survival of cutaneous melanoma patients." (PMID 30297743, 2018). "Covariates used in cutaneous melanomas (pT1 and pT4) were: Breslow’s classification, ulceration, mitotic rate, patients age and immunostaining results of HAS1 and HAS2." (PMID 27184066, 2016). "Our work delivers new information about hyaluronan metabolism in cutaneous melanoma and identifies HAS1 and HAS2 as possible prognostic factors in this aggressive cancer." (PMID 27184066, 2016). "Our previous work showed that decreased expression of hyaluronan in the cutaneous melanoma is due to decreased expression of HAS1 and HAS2 and increased expression of HYAL2." (PMID 27184066, 2016).
diabetes (2 papers, 2019 to 2023). "Enhanced intima hyperplasia in diabetes is mainly due to insulin signaling via homo-IR, associated with increased Has2 expression." (PMID 31562314, 2019).
emphysema (2 papers, 2022 to 2025). "The findings of this study do not provide a comprehensive explanation for the observed association between Has2 dysfunction and the subsequent development of acute-phase G-CSF and neutrophil increase, accompanied by severe emphysema formation." (PMID 41181120, 2025). "Taken together, these histological evaluations have revealed that Has2+/− mice are more susceptible to PPE-induced emphysema." (PMID 41181120, 2025). "A quantitative analysis using MLI revealed that the Has2+/− mice exhibited more severe emphysema at least 1 day after the administration of PPE compared with the WT mice." (PMID 41181120, 2025). "Further, the Has2+/− mice presented with enhanced emphysema development on histological analyses, with higher mean linear intercept values relative to the WT mice." (PMID 41181120, 2025). "To elucidate the protective role of HAS2 against emphysema, we initially evaluated the development of emphysema 1, 4, and 21 days after the administration of PPE." (PMID 41181120, 2025). "Based on these results, the increase in the G-CSF levels associated with Has2 dysfunction worsens emphysema formation and airway inflammation during the acute phase after PPE administration in the Has2+/−-KO mice." (PMID 41181120, 2025). "Therefore, Has2 dysfunction exacerbates neutrophilic airway inflammation and emphysema, thereby underscoring the protective role of HAS2 in a PPE-induced emphysema model." (PMID 41181120, 2025). "Results showed that the Has2+/− mice exhibited a more severe neutrophilic airway inflammatory reaction, higher degree of emphysema formation, and increased granulocyte-colony stimulating factor (G-CSF) with transforming growth factor beta 1 (TGF-β1) attenuation." (PMID 41181120, 2025). "Therefore, this study examined whether HAS2 dysfunction worsens airway inflammation and emphysema in a mouse COPD model." (PMID 41181120, 2025). "However, the specific impact of HAS2 on pulmonary emphysema progression remains unclear." (PMID 41181120, 2025). "Hyaluronan Synthase 2 (HAS2) has a protective effect on airway inflammation and emphysema induced by elastase in mice." (PMID 35250960, 2022). "In particular, whether the supply of HAS2 enzymes, HMW-HA, and anti-G-CSF Ab into the airway inhibits lung neutrophilic airway inflammation and emphysema should be examined." (PMID 41181120, 2025).
endometrioid ovarian cancer (2 papers, 2022 to 2023). "This applies to HAS1 and HAS2 to data of OS of patients with endometrioid ovarian cancer and of PFS of patients in grade 1." (PMID 35767191, 2022).